FDX2 (ferredoxin 2)
Description:
Electron donor, of the core iron-sulfur cluster (ISC) assembly complex, that acts to reduce the persulfide into sulfide during [2Fe-2S] clusters assembly on the scaffolding protein ISCU. The core iron-sulfur cluster (ISC) assembly complex is involved in the de novo synthesis of a [2Fe-2S] cluster, the first step of the mitochondrial iron-sulfur protein biogenesis (By similarity). This process is initiated by the cysteine desulfurase complex (NFS1:LYRM4:NDUFAB1) that produces persulfide which is delivered on the scaffold protein ISCU in a FXN-dependent manner (By similarity). Then this complex is stabilized by FDX2 which provides reducing equivalents to accomplish the [2Fe-2S] cluster assembly (By similarity). Finally, the [2Fe-2S] cluster is transferred from ISCU to chaperone proteins, including HSCB, HSPA9 and GLRX5 (By similarity). Essential for coenzyme Q biosynthesis: together with FDXR, transfers the electrons required for the hydroxylation reaction performed by COQ6.
Synonyms: FDX1L; MGC19604; MEOAL
Tractability: Small molecule: a structure with a bound ligand is known.
Gene: Protein-coding gene on chromosome 19 (10,309,916 to 10,316,015, reverse strand). Ensembl gene ENSG00000267673.
Subcellular location: Mitochondrion; Mitochondrion matrix
Pathways (Reactome):
Metabolism: Electron transport from NADPH to Ferredoxin; Endogenous sterols; Mitochondrial iron-sulfur cluster biogenesis; Pregnenolone biosynthesis
Disease: Defective CYP11A1 causes AICSR
Gene Ontology:
Molecular function: electron transfer activity; protein binding; 2 iron, 2 sulfur cluster binding; iron-sulfur cluster binding
Biological process: [2Fe-2S] cluster assembly; [4Fe-4S] cluster assembly; ubiquinone biosynthetic process; iron-sulfur cluster assembly; P450-containing electron transport chain
Cellular component: mitochondrion; iron-sulfur cluster assembly complex; mitochondrial matrix
Genetic constraint (gnomAD): Loss-of-function variants: 13 observed, 17.76 expected, observed/expected ratio (o/e) 0.73, 90% interval 0.47 to 1.16. The upper end of that interval is the gene's LOEUF score, 1.16, which puts it in group 5 of 6, group 1 being the genes least tolerant of losing a copy. Missense variants: 238 observed, 253.01 expected, observed/expected ratio (o/e) 0.94, 90% interval 0.85 to 1.05. Synonymous variants: 132 observed, 108.94 expected, observed/expected ratio (o/e) 1.21, 90% interval 1.05 to 1.4.
Homologues: Orthologues: chimpanzee FDX2 (99% identical), macaque FDX2 (95% identical), pig FDX2 (89% identical), dog FDX2 (85% identical), rat Fdx2 (81% identical), mouse Fdx2 (80% identical), guinea pig FDX2 (78% identical), zebrafish fdx2 (58% identical), tropical clawed frog fdx2 (57% identical), Caenorhabditis elegans Y73F8A.27 (46% identical), Drosophila melanogaster Fdx1 (46% identical). Paralogues in human: FDX1 (28% identical).
Diseases named in the same sentence as FDX2 in open-access papers:
FDX2 is named in the same sentence as 23 diseases in open-access papers, as found by Europe PMC text mining. Sharing a sentence is not in itself a finding about the gene and the disease. The quoted sentences say what the papers report.
Mitochondrial myopathy (7 papers, 2017 to 2025). "Pathogenic variants in FDX2 have been associated with autosomal recessive FDX2-related disorder characterized by mitochondrial myopathy with or without optic atrophy and leukoencephalopathy." (PMID 38444577, 2024). "FDX2, encoding a small protein involved along with FDXR in donating electrons to nascent ISCs, was the second gene in the Fe-S biogenesis pathway to be linked to a mitochondrial myopathy (OMIM #251900)." (PMID 38950322, 2024). "Pathogenic mutations of the FDX2 gene cause episodic mitochondrial myopathy with or without optic atrophy and reversible leukoencephalopathy (MEOAL, OMIM number: 251900)." (PMID 35883565, 2022). "FDX1L (also known as FDX2) can contribute to mitochondrial myopathy and/or neurological symptoms; however, no previous study has found associations of this factor with depressive disorder." (PMID 32555505, 2020).
optic atrophy (7 papers, 2020 to 2025). A disorder characterized by loss of optic nerve fibers. "Recessive mutations in FDX2 induces a complex phenotype consisting of optic atrophy, reversible leukoencephalopathy, myopathy, and axonal polyneuropathy." (PMID 33426505, 2020). "–28 Interestingly, variants in FDX2, encoding another mitochondrial ferredoxin (FDX2) have been associated with mitochondrial disease, including optic atrophy but without retinal involvement." (PMID 33938912, 2021). "The surprising number of patient families with FDXR mutations that have been discovered in such a short period of time raises the possibility that the FDXR/FDX1/FDX2 pathway may lie behind many cases of optic atrophy and ataxia with no previously identified cause." (PMID 32499495, 2020). "Specific role(s) for FDX2 in these disorders remain uncertain, but 2 studies reported mitochondrial muscle myopathy with or without optic atrophy and reversible leukoencephalopathy (MEOAL; OMIM #251900) in patients with FDX2 mutations." (PMID 39574227, 2025).
Friedreich ataxia (5 papers, 2019 to 2026). An inherited condition that affects the nervous system and causes movement problems. "We show that lowering levels of wild-type FDX2 through loss of one gene copy can ameliorate the growth of frataxin mutant C. elegans or the ataxia phenotype of a mouse model of Friedreich’s ataxia under normoxic conditions." (PMID 41372402, 2026). "These genetic and biochemical studies indicate that restoring the stoichiometric balance of frataxin and FDX2 through partial knockdown of FDX2 may be a potential therapy for Friedreich’s ataxia." (PMID 41372402, 2026). "To test whether lowering FDX2 levels could also improve disease phenotypes in a mouse model of Friedreich’s ataxia, we asked whether a 50% decrease in Fdx2 gene dosage would suppress the movement disorders of a frataxin mouse mutant." (PMID 41372402, 2026). "Finally, we demonstrate that reducing Fdx2 expression can alleviate neurological defects observed in a mouse model of Friedreich’s ataxia." (PMID 41372402, 2026). "The fact that FDX2 and FXN compete for an overlapping binding site may have implications for understanding Friedreich’s ataxia, which is most commonly due to lowered abundance of FXN, rather than differences in its amino acid sequence." (PMID 39632806, 2024). "We propose that this reconstitution recapitulates physiological conditions which provides a model for Fe-S cluster biosynthesis, clarifies the roles of FDX2 and FXN and may help develop Friedreich’s ataxia therapies." (PMID 31395877, 2019).
lactic acidosis (4 papers, 2018 to 2025). Metabolic acidosis characterized by the accumulation of lactate in the body. "Similar to the ISCU myopathy, mutations in the FDX1L gene which disrupts the initiation translation site of the FDX2 protein caused proximal muscle myopathy associated with myoglobinuria and lactic acidosis together with reduced activity of aconitase and affected complex II." (PMID 29511832, 2018).
Ataxia (2 papers, 2020 to 2026). Ataxia refers to impaired coordination of voluntary muscle movement. "We observed statistically significant improvement of ataxia phenotypes in the shFxn; Fdx2/+ double mutants." (PMID 41372402, 2026).
COVID-19 (2 papers, 2022 to 2024). A disease caused by infection with severe acute respiratory syndrome coronavirus 2. "Co-localization analysis identified LZTFL1, MUC4, OAS1, HLA-C, SLC22A31, FDX2, and MAPT as genes involved in COVID-19-mediated causation of MM." (PMID 38400850, 2024). "In addition to these chromosomes, the causal SNPS of COVID-19 hospitalization on MM are also located in many regions of chromosome 19, involving genes such as PSG5, SLC22A31, FDX2, MAPT and others." (PMID 38400850, 2024).
lung carcinoma (2 papers, 2022 to 2024). "Here, comparable to NFS1 amplification in lung cancer, we observed FDX2 gene amplification in a substantial fraction of ovarian cancer (OVC) cases, an observation not previously reported in other cancer types." (PMID 39151727, 2024). "Gene amplification revealed by our analysis of TCGA cohorts suggests a possible cancer-promoting role for FDX2 in OVC, analogous to NFS1 in lung cancers." (PMID 39151727, 2024).
ovarian carcinoma (2 papers, 2024 to 2026). A malignant neoplasm originating from the surface ovarian epithelium. "To assess these outcomes in cancer, we developed an ovarian cancer line with conditional KO of FDX2, a component of the core Fe-S assembly complex." (PMID 39151727, 2024). "Using inducible loss-of-function transplant models of a human ovarian cancer line, we show that FDX2 is required for tumor initiation and metastasis but not for growth of established tumors in mice." (PMID 42208897, 2026).
Adrenal insufficiency (1 paper, 2025). Insufficient production of steroid hormones (primarily cortisol) by the adrenal glands. "Mutations of FDX2 (which does not appear to participate in steroidogenesis) are associated with neurologic disorders but not with adrenal insufficiency." (PMID 39574227, 2025).
ISCU myopathy (1 paper, 2024). "The P144L mutation also causes iron deposition in the cells, similarly to what has been reported in ISCU myopathy, in agreement with the role of FDX2 in cellular iron homeostasis via its mitochondrial role in the maturation of cytosolic IRP1 to an aconitase." (PMID 39467201, 2024).
tumor (5 papers, 2022 to 2026). "Our findings highlight a differential requirement of Fe-S cluster biosynthesis for tumor metastasis versus growth and low oxygen-mediated mitigation of Fe-S protein loss promoted by FDX2 deficiency." (PMID 42208897, 2026). "In summary, these findings underline an indispensable role of FDX2 in tumor suppression and lipid homeostasis at both cellular and organismal levels without being a prerequisite for embryonic development." (PMID 39732391, 2024). "Some studies have found that FDXR with FDX2 deletion regulates P73 tumor suppressor via IRP2 to modulate aging and tumor suppression." (PMID 38898987, 2024).
myopathy (4 papers, 2018 to 2024). A disease of the muscle in which the muscle fibers do not function properly. "Relevant to FDX2, one myopathy patient reportedly harbored a homozygous c1A > T mutation in FDX2, which disrupts the ATG translation initiation codon and severely decreases FDX2 protein levels, but that patient recovered following treatment of symptoms." (PMID 39151727, 2024).
cancer (3 papers, 2024 to 2026). A tumor composed of atypical neoplastic, often pleomorphic cells that invade other tissues. "On the other hand, recent studies report that loss/suppression of FDX2, another component of the core Fe-S assembly complex, by RNAi or genome-editing suppressed proliferation of some human cancer or immortalized lines." (PMID 39151727, 2024). "Dependency Map (DepMap) dataset analysis suggested that OVC cells showed the greater susceptibility to FDX2-KO than other pan-cancer groups." (PMID 39151727, 2024). "Further studies are needed to understand how FDX2 deficiency affects healthy normal cells/tissues in order to develop novel strategies to therapeutically target Fe-S and related metabolism in ovarian and other cancers." (PMID 39151727, 2024). "However, how FDX2 loss alters cellular functions, including proliferation/survival, remains unclear in other forms of cancer." (PMID 39151727, 2024). "Here we report analysis suggesting a stage-specific requirement for FDX2, a critical component of the Fe-S cluster assembly complex, in cancer progression." (PMID 42208897, 2026). "Nevertheless, further study is needed to evaluate the possibility of targeting FDX2 therapeutically in cancer." (PMID 39151727, 2024). "Analysis of The Cancer Genome Atlas (TCGA) dataset revealed that the frequency of FDX2 alteration was highest in OVC compared to other cancer types, with amplification the most highly reported alteration." (PMID 39151727, 2024). "Specifically, upon entering the cancer cells either through interactions between Zn and ZFPs directing them toward Mito, ZCE disrupted the preparation of Fe-S protein in mitochondrial electron transport chain (ETC) through down-regulating the expression of FDX2/LIAS and ZIP7 to activate Znproptosis." (PMID 40225560, 2025).
metabolic disease (1 paper, 2024). A congenital disorder (due to inherited enzyme abnormality) or acquired (due to failure of a metabolically important organ) disorder resulting from an abnormal metabolic process. "In addition, the 4 VUS identified in this study (CFTR: rs1800120, TBC1D24: rs754558646, HTT: rs779780620, and FDX2: rs897162037) were found to coexist with several other P/LP variants or VUS in genes associated with cardiovascular/metabolic diseases or CoQ deficiency." (PMID 38844616, 2024).
neurologic disorders (1 paper, 2025). "FDX2 has been implicated in several neurological diseases, including Friedreich's ataxia and Parkinson's disease." (PMID 39574227, 2025).
FDX2 also shares sentences with these, for which no sentence is quoted: Leukoencephalopathy (3 papers); depression (2); autosomal recessive disease (1); axonal neuropathy (1); inflammation (1); metabolic myopathy (1); mitochondrial disease (1); movement disorder (1).